FLOT1 (flotillin 1)
Diseases named in the same sentence as FLOT1 in open-access papers (continued):
Sharing a sentence is not in itself a finding about the gene and the disease.
non-small cell lung carcinoma (6 papers, 2014 to 2024). A group of at least three distinct histological types of lung cancer, including non-small cell squamous cell carcinoma, adenocarcinoma, and large cell carcinoma. "We performed a correlation analysis of caveolin-1, stomatin, and flotillin-1 mRNA expression in the whole group of non-small cell lung cancer (NSCLC) specimens and in its subgroups in accordance with the clinicopathological characteristics of the specimens." (PMID 24533441, 2014). "Moreover, FLOT1 promotes therapy resistance through PD–L1 immune escape via the STING signaling pathway in non-small cell lung cancer." (PMID 39404386, 2024).
clear cell renal cell carcinoma (5 papers, 2015 to 2023). "Lv noted that the long non-coding RNA TUG1 promotes cell proliferation through the MIR-31-5p/FLOT1 axis in clear cell renal cell carcinoma and inhibits apoptosis and autophagy." (PMID 35910212, 2022). "Literature search has revealed different targets of miR-124 in different tissues and tumor types, such as Foxq1 in nasopharyngeal cancer, CCAAT/enhancer-binding protein-α in macrophages, PTBP1 in neuronal differentiation, and CAV1 and FLOT1 in renal clear cell carcinoma." (PMID 28212569, 2017). "(2015 May) miRNA-target network reveals miR-124as a key miRNA contributing to clear cell renal cell carcinoma aggressive behaviour by targeting CAV1 and FLOT1." (PMID 37219053, 2023).
glioma (5 papers, 2019 to 2024). A benign or malignant brain and spinal cord tumor that arises from glial cells (astrocytes, oligodendrocytes, ependymal cells). "One study found that Flotilin-1 (FLOT1), upregulated in gliomas and associated with advanced progression and poor prognosis, is stabilized by m6A methylation, with WTAP acting as the writer." (PMID 38474421, 2024). "To elucidate the mechanism underlying the role of FLOT1 in glioma, we performed GO enrichment and KEGG pathway analyses." (PMID 36647700, 2023). "In this study, we first reported FLOT1 as a potential molecular marker in the development of glioma, as evidence suggested that FLOT1 is closely associated with clinicopathological features and immune surveillance of gliomas and promoted glioma cell proliferation, invasion and migration." (PMID 36647700, 2023). "The silencing of FLOT1 led to reduced glioma cell proliferation, highlighting the significance of WTAP in glioma biology." (PMID 38474421, 2024). "While overexpression of FLOT1 increased the proliferation, migration and invasiveness of glioma cells via MAPK signalling." (PMID 36647700, 2023). "Western blots were employed to demonstrate the expression of the exosome markers CD63 and Flotillin-1 in glioma patients' and normal donors' plasma exosomes isolated by two-step DGU." (PMID 31380286, 2019). "Additionally, IGF2BP2 stabilizes transcripts like NUP214 and FLOT1, influencing glioma progression and TMZ resistance." (PMID 38474421, 2024). "Here, in this study, we find that the expression level of FLOT1 in GBM tissue was much higher than that in normal brain, and the expression was even higher in the more aggressive subtypes and IDH status of glioma." (PMID 36647700, 2023). "In this study, we aimed to understand the relationship among SDC1, TGM2, FLOT1 and BHMT in modulating glioma autophagy and investigated their roles in regulating the radiosensitivity of glioblastoma by affecting the fusion of autophagosomes and lysosomes." (PMID 37441590, 2023). "More interestingly, the Gliovis database showed that FLOT1 was positively correlated with SDC1 expression and BHMT was positively correlated with TGM2 expression in glioma tissues." (PMID 37441590, 2023). "Both CD63 and Flotillin-1 were detected in normal donors, grade 4 GBM and grade 3 glioma patients' exosomes, indicating again that our DGU protocol allows the isolation of exosomes." (PMID 31380286, 2019). "In this study, we found that FLOT1 is markedly upregulated in glioma tissue, compared with normal brain tissues." (PMID 36647700, 2023). "Kaplan-Meier curves showed that both FLOT1 and BHMT could mediate the worse prognosis of glioma patients." (PMID 37441590, 2023).
lymph node metastasis (5 papers, 2009 to 2025). "Herein, we found that FLOT1 was aberrantly overexpressed in the tumors of NPC patients with lymph node metastasis at diagnosis, and was associated with poor overall and disease-free survivals." (PMID 26646322, 2016). "Chi-square test revealed that FLOT1 expression was significantly associated with the lymph node metastasis status (P < 0.001), suggesting that overexpression of FLOT1 is clinically associated with lymph node metastasis in NPC." (PMID 26646322, 2016). "Indeed high flotillin-2 expression has been shown to be associated with lymph node metastasis and melanoma progression and expression of flotillin-1 and -2 was induced during G-CSF induced myeloid progenitor cell proliferation and granulocyte differentiation." (PMID 20027317, 2009). "Additionally, high expressionlevelof Flotillin-1 was also found to be significantly associated with lymph node metastasis (OR =6.30; 95% CI:3.15-12.59, p<0.001), distant metastasis (OR =6.02; 95% CI: 1.50-24.06, p=0.01) and more advanced TNM stage (OR =4.69; 95% CI: 2.74-8.03, p<0.001)." (PMID 28881760, 2017). "In tongue squamous cell cancer, the expression of Flotillin-1 was correlated with pathological stage, depth of invasiveness, lymph node metastasis, recurrence and shorter survival." (PMID 35990908, 2022). "High levels of FLOT1 expression also predicted poorer overall survival (P = 0.038; HR (95% CI) = 1.88 (1.02–3.48)) in the subgroup of patients with lymph node metastasis." (PMID 26646322, 2016). "In this study, we found that high expression of FLOT1 significantly correlated with lymph node metastasis and poor survival in human NPC." (PMID 26646322, 2016). "Importantly, FLOT1 expression levels were more robustly elevated in NPC tissues from patients with lymph node metastasis (LN+) than the LN− cases, suggesting that FLOT1 might play a role in lymph node metastasis in NPC." (PMID 26646322, 2016). "Notably, high levels of FLOT1 expression were reported to significantly correlate with clinical N (lymph node metastasis) and M (distant metastasis) classification in several human cancers, suggesting that FLOT1 might contribute to cancer metastasis." (PMID 26646322, 2016). "We further assessed whether FLOT1 expression was clinically correlated with lymph node metastasis in 169 paraffin-embedded, archived NPC tissues, including 57 lymph node metastasis-negative (LN−) cases and 112 lymph node metastasis-positive cases (LN+)." (PMID 26646322, 2016).
neuroblastoma (5 papers, 2010 to 2022). Neuroblastoma (NB) is the most common solid, extracranial childhood tumor. "Flotillin-1 has been reported to interact with ALK and regulate its lysosomal degradation through endocytosis in neuroblastoma cells." (PMID 35508387, 2022).
Alzheimer disease (4 papers, 2020 to 2025). A progressive, neurodegenerative disease characterized by loss of function and death of nerve cells in several areas of the brain leading to loss of cognitive function such as memory and language. "However, aside from GBM, FLOT1 was reported to play a role in neurological disorders, for example Alzheimer's disease, Parkinson, multiple sclerosis and biological ageing." (PMID 36647700, 2023). "Thus, salivary flotillin-1 may serve as a promising noninvasive biomarker for the early diagnosis of Alzheimer’s disease." (PMID 41515556, 2025).
bladder cancer (4 papers, 2017 to 2023). "In bladder cancer, up-regulation of FLOT1 could also reverse the suppressed cell proliferation caused by miR-608 via activating AKT signaling." (PMID 30820716, 2019). "Further, FLOT1 was determined to be overexpressed in bladder cancer and its expression correlated with migration and invasion characteristics of the cells." (PMID 36805539, 2023). "In our study, we discovered that FLOT1 was widely over-expressed in bladder cancer TMAs, and was significantly down-regulated and accompanied with the decreased p-AKT and p-FOXO3a in miR-608 treated xenograft tumor." (PMID 28549468, 2017). "Furthermore, miR-608 affected the downstream AKT/FOXO3a signaling pathway by targeting FLOT1, thus inhibiting the proliferation of bladder cancer." (PMID 33425728, 2020). "Furthermore, we revealed that miR-608 could suppress the proliferation and tumorigenesis of bladder cancer cells via targeting FLOT1." (PMID 28549468, 2017). "Moreover, the overexpression of FLOT1 could dramatically promote the proliferation of prostate and bladder cancer cells, and also accelerate the invasion, migration of bladder cancer cells." (PMID 28549468, 2017).
depression (4 papers, 2019 to 2024). "Among other TWAS-significant shared genes, FLOT1 was previously implicated in depression and aerodigestive squamous cell carcinoma." (PMID 37143087, 2023). "To this end we used Flot1 KO mice as model of genetic Flot1 deficiency and characterized depression‐like behavior within a well‐defined battery of tests for behavioral phenotyping." (PMID 29667320, 2019). "Flotillin-1 overexpression in patients with depression would be likely to facilitate SERT recycling, increasing plasma membrane levels and facilitate continued serotonin uptake into the cell." (PMID 35280519, 2021). "Flotillin-1 (or reggie-2) is upregulated in the brain and peripheral tissues of depression sufferers." (PMID 35280519, 2021). "Based upon these observations, we considered that Flot1 might be relevant within the “gene × environment” interaction framework which is largely considered to account for the multifactorial origins of psychiatric disorders, including depression." (PMID 29667320, 2019). "Here we identified Flotillin‐1 as novel physical interaction partner of SERT in the mouse brain and demonstrate a role for Flot1 as a mitigating factor in chronic CORT‐induced SERT regulation and depression‐like behavior." (PMID 29667320, 2019).
ovarian carcinoma (4 papers, 2023 to 2025). A malignant neoplasm originating from the surface ovarian epithelium. "Association of serum FLOT1 protein with the clinicopathological features of patients with ovarian cancer." (PMID 40066501, 2025). "Association of serum FLOT1 protein with the clinical features of patients with ovarian cancer." (PMID 40066501, 2025). "Correlation between CA125 and FLOT1 in patients with ovarian cancer." (PMID 40066501, 2025). "Moreover, TNPO1, ACLY, NME1, FLOT1, and KLC4 are proteins already known to be involved in epithelial ovarian cancer." (PMID 37775701, 2023).
renal cell carcinoma (4 papers, 2014 to 2021). "lncRNA TUG1 suppressed miR-196A, regulated the MIR-31-5p/flotillin 1 (FLOT1) axis, or regulated yes‐associated protein (YAP) to promote the proliferation and migration of renal cell carcinoma." (PMID 34039257, 2021). "In our current study, we revealed that FLOT1 was commonly over-expressed in all three types of renal cell cancer tissues." (PMID 24886554, 2014). "Moreover, recent profile studies showed that miR-506 regulated the biological behavior of cancer cells by targeting FLOT1 and GATA6 in renal cell cancer and oral squamous cell cancer." (PMID 26452129, 2015).
schizophrenia (4 papers, 2018 to 2025). A major psychotic disorder characterized by abnormalities in the perception or expression of reality. "Methylation level at three top-sites was associated with expression levels of genes that have been previously linked to psychiatric or behavioral traits in GWASs: FLOT1 (schizophrenia), TUBB (schizophrenia), and PLXNA2 (general risk tolerance)." (PMID 33420481, 2021). "Similarly, FLOT1, which exhibited reduced expression in association with genetic risk for schizophrenia, has been found to promote the formation of hippocampal glutamatergic synapses, which appear to be decreased in the disorder." (PMID 30419947, 2018). "One can speculate that existence of protein-protein interactions, close proximity of these genes within the nucleus and shared biological function, makes the FLOT1 gene (as well as other genes from this set of 580 genes) a potential candidate, linked to schizophrenia." (PMID 31784692, 2019). "Only HLA-C and FLOT1 are inferred to have direct causal effects on schizophrenia risk, and all other 15 peripheral genes (OR2J3 excluded) may have causal effects on schizophrenia that only are mediated by FLOT1 and/or HLA-C expression." (PMID 40270926, 2025).
colon cancer (3 papers, 2017 to 2024). "The candidate proteins included caveolae-associated integral membrane protein, flotillin-1 (FLOT1); transport cargo-associated protein, dynein intermediate chain 1 (DYNC1); and CD59 glycoprotein (CD59), which may give a clue specific internalization of calgranulin B into colon cancer cells." (PMID 28036279, 2017). "Therefore, while flotillin-1 may interact with calgranulin B, it does not appear to be a key player in the internalization of only calgranulin B into colon cancer cells." (PMID 28036279, 2017).
colorectal cancer (3 papers, 2014 to 2023). A primary or metastatic malignant neoplasm that affects the colon or rectum. "While we were able to detect the presence of EV markers Syntenin-1 and Flotillin-1 in our positive control sample, concentrated media from colorectal cancer cells (DiFi), we were unable to detect these proteins in our DGUC-purified lipoproteins (i.e., VLDL, LDL, HDL)." (PMID 36626966, 2023).
esophageal cancer (3 papers, 2024 to 2025). A primary or metastatic malignant neoplasm involving the esophagus. "FLOT1 is upregulated in various malignancies, including endometrial, cervical, renal, breast, lung, nasopharyngeal, and esophageal cancers, where it functions as an oncogene." (PMID 40335491, 2025). "This consistency was observed when FLOT1 inhibition effectively blocked Fp infection-induced migration, invasion, and fatty acid accumulation in esophageal cancer cells." (PMID 39193618, 2024). "To confirm the relationship between Circ_0003855 and EC, we purchased the Human esophageal carcinoma cell line Eca109 and normal human esophageal epithelial cells HEEC, and the expression levels of Circ_0003855, miR-622, and FLOT1 were detected." (PMID 38686057, 2024).
glioblastoma (3 papers, 2022 to 2023). The most malignant astrocytic tumor (WHO grade IV). "However, the expression and function of FLOT1 in glioblastomas (GBM) has not been elucidated." (PMID 36647700, 2023).
melanoma (3 papers, 2009 to 2024). A malignant, usually aggressive tumor composed of atypical, neoplastic melanocytes. "Consistently, data mined from TCGA consistently show that a higher level of lipid raft (FLOT1) expression correlates with worse survival in melanoma." (PMID 39343834, 2024). "In contrast, genes that were commonly downregulated in sensitive and resistant melanoma spheroids, including MMP16, IGF1R and FLOT1, are associated with malignancy, and several studies have reported that these genes are related to the aggressive behaviour of melanoma." (PMID 32613561, 2020). "Most of the shared genes (40 genes) were downregulated including MMP16, IGF1R, FLOT1 and CEP19 and are functionally involved in several types of cancers, including melanoma." (PMID 32613561, 2020).
multiple sclerosis (3 papers, 2017 to 2023). A progressive autoimmune disorder affecting the central nervous system resulting in demyelination. "We screened the presence of anti-FLOT-1/2 antibodies in 282 patients fulfilling diagnostic criteria for multiple sclerosis (252 sera and 50 CSF), and 260 controls (including healthy donors and patients with other neurological disorders)." (PMID 37091585, 2023). "Further studies are needed to understand the clinical and pathological relevance of anti-flotillin-1/2 autoantibodies in multiple sclerosis." (PMID 37091585, 2023). "We identified six multiple sclerosis patients with antibodies against the flotillin-1/2 complex (2.1%) and one multiple sclerosis patient with antibodies against anoctamin-2 (0.35%)." (PMID 37091585, 2023). "We confirm that antibodies targeting the flotillin-1/2 complex are present in a subgroup of patients with multiple sclerosis." (PMID 37091585, 2023). "In our cohort, multiple sclerosis patients with anti-FLOT-1/2 autoantibodies in serum are found in 2.1% of the patients." (PMID 37091585, 2023). "Our study aims to analyse the frequency and clinical relevance of antibodies against neurofascin-155, anoctamin-2 and flotillin-1/2 complex in multiple sclerosis." (PMID 37091585, 2023). "Regarding CSF samples, we detected anti-FLOT1/2 antibodies in one more multiple sclerosis patient (1/50, 2%)." (PMID 37091585, 2023). "This suggests that anti-FLOT-1/2 antibodies are specific of multiple sclerosis." (PMID 37091585, 2023). "Here, we report on autoantibodies against the flotillin-1/2 complex detected in patients referred for anti-AQP4 testing, most of whom turned out to suffer from bona fide multiple sclerosis presenting with ON." (PMID 28645295, 2017). "Despite anti-FLOT1/2 antibodies are very infrequent in multiple sclerosis, we did not detect any positive patient in the control group (that included 260 sera from healthy donors and patients with other neurological disorders)." (PMID 37091585, 2023).
breast tumor (2 papers, 2018 to 2019). "Interestingly, we also found an increase in the expression of both flotillin-1 and flotillin-2 in breast tumor cells after treatment." (PMID 31562347, 2019). "Interestingly, flotillin-1 translation is controlled by the micro-RNA miR-124, which is frequently downregulated in breast tumors, correlating with increased flotillin-1 expression." (PMID 29642469, 2018).
diabetes (2 papers, 2019 to 2023). "To elucidate the potential mechanisms involved in the miR-124 regulation of microglial behavior in early diabetes, we detected the expression of PU.1 and Flot1 in diabetic rat retinas and rat primary microglial cells with miR-124 treatment." (PMID 36768614, 2023). "Therefore, PU.1 and Flot1 are obvious effectors of miR-124-mediated microglial function not only in neurodegeneration but also in diabetes." (PMID 36768614, 2023). "Similarly, we observed that Flot1, a direct binding target of miR-124, was suppressed in diabetic retinae and the rat primary microglial cells after miR-124 treatment." (PMID 36768614, 2023). "Given that transcription factor PU.1 and lipid raft protein Flot1, which are indirect or direct targets of miR-124, are involved in the miR-124 regulation of microglial behaviors in neurodegenerative disease models, we investigated if similar regulatory mechanisms are valid in diabetes." (PMID 36768614, 2023).
ischemia (2 papers, 2020). A hypoperfusion of the BLOOD through an organ or tissue caused by a PATHOLOGIC CONSTRICTION or obstruction of its BLOOD VESSELS, or an absence of BLOOD CIRCULATION. "Analogous to the in vivo model, intracardiac EVs obtained from isolated rat hearts subjected to ex vivo ischemia displayed reduced Cx43 levels, whereas Flotillin-1 levels and EVs amount (NTA) were maintained similar in control and ischemic hearts." (PMID 33097557, 2020). "Consistent with the data on NTA, western blot analysis demonstrated that the expression levels of exosome markers CD9 and Flot1 were significant higher in ischemia group, compared to sham control, confirming an increase of exosome release post ischemia." (PMID 32117296, 2020). "Western blot analysis also revealed that CB839 administration significantly suppressed the release of exosomes, ascertained by the reduction of CD9 and Flot1 protein levels in ischemia with CB839 treatment group, compared with that in ischemia with DMSO treatment group." (PMID 32117296, 2020).
osteosarcoma (2 papers, 2015 to 2021). A usually aggressive malignant bone-forming mesenchymal neoplasm, predominantly affecting adolescents and young adults. "The expression of FLOT1 (flotillin) was also significantly repressed in osteosarcoma cell lines (P = 0.044) compared to Ewing." (PMID 26095524, 2015).